SEMA3G (semaphorin 3G)
Description:
Has chemorepulsive activities for sympathetic axons. Ligand of NRP2 (By similarity).
Synonyms: FLJ00014; sem2
Tractability: Antibody: UniProt places it where antibodies can reach, with medium confidence; UniProt predicts a signal peptide or a membrane-spanning region; its Gene Ontology location is reachable by antibodies, with medium confidence.
Gene: Protein-coding gene on chromosome 3 (52,433,035 to 52,445,103, reverse strand). Ensembl gene ENSG00000010319.
Subcellular location: Secreted
Gene Ontology:
Molecular function: protein binding; chemorepellent activity; neuropilin binding; semaphorin receptor binding; signaling receptor binding
Biological process: axon guidance; negative chemotaxis; negative regulation of axon extension; neural crest cell migration; positive regulation of cell migration; semaphorin-plexin signaling pathway; forebrain development
Cellular component: extracellular exosome; plasma membrane; extracellular region
Genetic constraint (gnomAD): Loss-of-function variants: 70 observed, 84.82 expected, observed/expected ratio (o/e) 0.83, 90% interval 0.68 to 1.01. The upper end of that interval is the gene's LOEUF score, 1.01, which puts it in group 4 of 6, group 1 being the genes least tolerant of losing a copy. Missense variants: 1,002 observed, 1,073.8 expected, observed/expected ratio (o/e) 0.93, 90% interval 0.88 to 0.98. Synonymous variants: 416 observed, 439.88 expected, observed/expected ratio (o/e) 0.95, 90% interval 0.87 to 1.03.
Homologues: Orthologues: chimpanzee SEMA3G (99% identical), macaque SEMA3G (98% identical), rabbit SEMA3G (88% identical), dog SEMA3G (88% identical), pig SEMA3G (88% identical), mouse Sema3g (87% identical), rat Sema3g (87% identical), guinea pig SEMA3G (86% identical), zebrafish sema3bl (56% identical). Paralogues in human: SEMA3E (50% identical), SEMA3A (45% identical), SEMA3B (45% identical), SEMA3D (43% identical), SEMA3F (42% identical), SEMA3C (40% identical), SEMA4G (29% identical), SEMA4D (28% identical), SEMA4C (28% identical), SEMA4B (27% identical), SEMA4F (26% identical), SEMA5B (26% identical), and 7 more.
Diseases named in the same sentence as SEMA3G in open-access papers:
SEMA3G is named in the same sentence as 34 diseases in open-access papers, as found by Europe PMC text mining. Sharing a sentence is not in itself a finding about the gene and the disease. The quoted sentences say what the papers report.
glioma (10 papers, 2008 to 2023). A benign or malignant brain and spinal cord tumor that arises from glial cells (astrocytes, oligodendrocytes, ependymal cells). "SEMA3G belongs to the family of class-3 semaphorins, and studies indicate that this gene is linked to kidney diseases, suggesting important roles with neuropilin and plexin families in the etiology of cancer, and it is also an inhibitor of glioma progression by competing with VEGF for receptor NRP1." (PMID 35565241, 2022). "There are few reports on the role of SEMA3G as an oncogene, and SEMA3G prevents tumor cell migration and invasion in gliomas." (PMID 36882799, 2023). "Yet a later study reported the opposite by demonstrating positive correlations of Sema3B, Sema3G and neuropilin-2 with prolonged survival in glioma patients." (PMID 23050142, 2012). "SEMA3G was found to be the only significant prognostic marker in gliomas when a multivariate analysis was performed." (PMID 18781179, 2008). "Among the tested semaphorins, SEMA3B and SEMA3G mRNA levels proved to be a prognostic marker for OS in our cohort including 11 low-grade and 27 high-grade gliomas (P=0.029 and P=0.016, respectively)." (PMID 18781179, 2008). "SEMA3G has anti-migration and anti-invasion effects on gliomas, and is a prognostic gene of KIRC." (PMID 36059531, 2022). "On the other hand, glioma patients who expressed lower levels of Sema3g showed shortened survival." (PMID 35223842, 2022). "In contrast to our results, SEMA3G inhibits cell migration and invasion in glioma." (PMID 32260415, 2020). "Similarly, an overexpression of or an exogenous stimulation by Sema3G in human U251 glioma cells is sufficient to inhibit migration and invasion, suggesting a cell autonomous or paracrine mechanism." (PMID 23050142, 2012). "One can speculate that SEMA3D and SEMA3G could have similar properties and behave like anti-angiogenic proteins in gliomas." (PMID 18781179, 2008). "However, SEMA3G was reported to exert anti-tumor effects in migration and invasion of glioma." (PMID 38070142, 2023). "In conclusion, SEMA3B, SEMA3G and NRP2 expressions were related to prolonged survival of adult patients with glial tumours." (PMID 18781179, 2008). "Statistical analysis indicated that SEMA3B, SEMA3G and NRP2 expressions were related to prolonged survival and that SEMA3D expression was reduced in high-grade as compared with low-grade gliomas." (PMID 18781179, 2008). "Moreover, in the study by Karyian-Tapon and co-authors, higher mRNA expression of SEMA3B, SEMA3G and NRP2 were related to prolonged survival of patients with the diagnosis of glial tumors." (PMID 33036421, 2020). "Moreover, to our knowledge, SEMA3D, SEMA3E, SEMA3F and SEMA3G expressions in human gliomas were not studied." (PMID 18781179, 2008).
breast cancer (5 papers, 2008 to 2025). A primary or metastatic malignant neoplasm involving the breast. "Thus, the concentration of recombinant sema3D found in the conditioned medium of either MDA-MB-231 breast cancer cells or in MDA-MB-435 melanoma cells was significantly lower than the concentrations of sema3F or sema3G." (PMID 18818766, 2008).
clear cell renal cell carcinoma (4 papers, 2021 to 2025). "The primary purpose was to unveil how the miR-146b-5p/SEMA3G axis works in clear cell renal cell carcinoma (ccRCC)." (PMID 36882799, 2023). "Similarly, in clear cell renal cell carcinoma, miR-146b-5p promoted tumor growth by inhibiting SEMA3G, further highlighting its dual role in cancer and inflammation." (PMID 40450371, 2025). "In addition, a previous study showed a four immune-related genes signature based on CXCL2, SEMA3G, PDGFD, and UCN is closely associated with the prognosis of renal clear cell carcinoma." (PMID 34030645, 2021).
Obesity (4 papers, 2015 to 2024). Accumulation of substantial excess body fat. "The most significantly different genes included F13a1 and Sema3g, which have previously been associated with adipogenesis and obesity." (PMID 39551140, 2024). "Several Sema3 members have been reported to regulate obesity by regulating adipogenesis (with an inhibitory role for Sema3A and a stimulatory role for Sema3G) and hypothalamic melanocortin circuits development (mutations of Sema3 and their receptors resulting in early onset of obesity)." (PMID 32781674, 2020). "Therefore, knockdown of Sema3G by shRNA ameliorates obesity, hepatosteatosis, and insulin resistance." (PMID 35045890, 2022). "Additionally, they proved that Sema3G inhibited HFD-induced obesity through the PI3K/Akt/GSK3β signaling pathway in adipose tissue and the AMPK/SREBP-1c pathway in the liver." (PMID 32781674, 2020). "Moreover, serum levels of Sema3G are elevated in individuals with obesity." (PMID 35045890, 2022).
Insulin resistance (2 papers, 2022 to 2023). Increased resistance towards insulin, that is, diminished effectiveness of insulin in reducing blood glucose levels. "In addition, Sema3G has opposing roles in adipogenesis: its plasma levels are increased in obese patients, while its deletion protects mice from HFD-induced weight and fat gain, insulin resistance and glucose tolerance and liver lipogenesis." (PMID 37121509, 2023).
Alzheimer disease (1 paper, 2022). A progressive, neurodegenerative disease characterized by loss of function and death of nerve cells in several areas of the brain leading to loss of cognitive function such as memory and language. "However, it was shown that SEMA3G is reduced in the CSF of patients with Alzheimer’s disease, which might contribute to the impairment of the structure and the plasticity of synapses." (PMID 36052089, 2022).
Arthritis (1 paper, 2022). Inflammation of a joint. "In vivo, Sema3G−/− mice displayed mild CIA and CAIA, and Sema3G administration exacerbated arthritis in CAIA." (PMID 35659346, 2022). "Although the severity of CIA and CAIA was mitigated in Sema3G−/− mice, antibody-mediated neutralization of Sema3G after the initiation of arthritis would be valuable in determining whether Sema3G could serve as a therapeutic target." (PMID 35659346, 2022). "Herein, we examined the gene-expression profiles of peripheral blood CD4+ T cells in 28 treatment-naïve RA patients before and after MTX treatment and evaluated the roles of one of the differentially expressed genes, semaphorin 3G (Sema3G), in murine experimental arthritis models." (PMID 35659346, 2022). "Therefore, it is possible that the Sema3G–Nrp2 axis also plays a role in T cell-mediated immune responses during arthritis." (PMID 35659346, 2022). "Finally, we assessed whether the local administration of Sema3G affects the severity of arthritis and macrophage migration and proliferation in vivo." (PMID 35659346, 2022). "Therefore, we hypothesized that Sema3G upregulates Snord89 to facilitate macrophage proliferation, resulting in aggravation of arthritis." (PMID 35659346, 2022). "Since we next sought to dissect the mechanisms by which Sema3G aggravates CIA, we employed CAIA, in which adaptive immunity is less critical in the development of arthritis." (PMID 35659346, 2022). "Second, Sema3G-mediated immune regulation during arthritis has not been addressed adequately." (PMID 35659346, 2022).
autoimmune disease (1 paper, 2022). A disorder resulting from loss of function or tissue destruction of an organ or multiple organs, arising from humoral or cellular immune responses of the individual to their own tissue constituents. "Although several studies have suggested that semaphorins are pivotally involved in autoimmune diseases, the role of Sema3G in this context is yet to be elucidated." (PMID 35659346, 2022).
brain tumor (1 paper, 2025). "Hence, our work establishes a new paradigm for SEMA3G-mediated ECs-GSCs communication, which will help in the development of promising therapeutic strategies to improve the treatment of this highly lethal brain tumor." (PMID 40533501, 2025).
cognitive disorder (1 paper, 2020). A disease affects cognitive processes. "Therefore, we propose Sema3g as a potential biomarker for the early stages of ALS/FTD and a potential therapeutic target in various cognitive disorders." (PMID 32184412, 2020).
diabetes (1 paper, 2016). "The glomerular function was worse in mice lacking Sema3G when we induced acute inflammatory kidney injury and diabetes." (PMID 27180624, 2016). "When these mice were injected with lipopolysaccharide to induce acute inflammation or streptozotocin to induce diabetes, the lack of Sema3G resulted in increased albuminuria." (PMID 27180624, 2016).
diabetic nephropathy (1 paper, 2016). "Taken together, our results surmise that the Sema3G protein is secreted by podocytes and protects podocytes from inflammatory kidney diseases and diabetic nephropathy." (PMID 27180624, 2016).
kidney cancer (1 paper, 2022). Primary or metastatic malignant neoplasm involving the kidney. "We observed that the mRNA expression level of ETV4 was significantly increased and the expression levels of SH2B3, FATE1, GRK5, MALL, HRH2, SEMA3G and SLC10A6 were decreased prominently in kidney cancer cells when compared with HK2 cell line." (PMID 36059531, 2022). "Furthermore, we detected the mRNA and protein expression levels of 8 epi-PCGs (ETV4, SH2B3, FATE1, GRK5, MALL, HRH2, SEMA3G and SLC10A6) in 4 human kidney cancer cell lines (786-O, A498, Caki-1 and ACHN) and the normal human renal tubular epithelial cell line HK2." (PMID 36059531, 2022).
kidney injuries (1 paper, 2016). "It would be interesting to speculate that a balance between the expression of the other semaphorins including Sema3A, which is pro-inflammatory, and Sema3G, which is anti-inflammatory, is important in the development of kidney injuries." (PMID 27180624, 2016).
melanoma (1 paper, 2008). A malignant, usually aggressive tumor composed of atypical, neoplastic melanocytes. "MDA-MB-435 melanoma cells express predominantly np2, a receptor for sema3F and sema3G and very little if any np1." (PMID 18818766, 2008).
osteoarthritis (1 paper, 2022). A noninflammatory degenerative joint disease occurring chiefly in older persons, characterized by degeneration of the articular cartilage, hypertrophy of bone at the margins and changes in the synovial membrane. "It was determined that semaphorin 3G is expressed in RA but not in the osteoarthritis synovium; its receptor neuropilin-2 is primarily expressed on activated macrophages." (PMID 35659346, 2022).
prostate carcinoma (1 paper, 2024). A carcinoma that arises from epithelial cells of the prostate gland. "In contrast, Kunitz-type protease inhibitor 2 (SPINT2) and prostate cancer, as well as Semaphorin-3G (SEMA3G) and CRC, were shown to have distinct variants at the gene target (i.e. PPH3 > 0.8)." (PMID 38527997, 2024).
thymoma (1 paper, 2025). A neoplasm arising from the epithelial cells of the thymus. "Notably, we observed that all SEMAs, except SEMA3G, had significant correlations with TMB in thymoma." (PMID 40103807, 2025).
tumor (20 papers, 2008 to 2025). "Taken together, the current data elucidated that ncRNA-caused downregulation of SEMA3G markedly linked to favorable prognosis and tumor immune infiltration in KIRC." (PMID 38070142, 2023). "Collectively, our current findings indicated that ncRNA-caused downregulation of SEMA3G linked to poor prognosis and tumor immune infiltration in KIRC." (PMID 38070142, 2023). "Several semaphorins including Sema3a, Sema3f, Sema3g and Sema6a have been reported to exert tumor growth-inhibiting activities while several others such as Sema4d and Sema6d have been associated with tumor-promoting functions in various cancer types." (PMID 35223842, 2022). "Furthermore, SEMA3G was markedly linked to tumor immune infiltration and expression of immune checkpoints in KIRC." (PMID 38070142, 2023). "All these data suggested that SEMA3G was statistically linked to tumor immune infiltration or immune checkpoints in KIRC, which might provide key clues for improving the efficacy of immunotherapy in KIRC in the future." (PMID 38070142, 2023). "The SEMA3G in the cerebrospinal fluid (CSF) of GBM patients was also significantly lower compared to that of non-tumor patients." (PMID 40533501, 2025). "Before evaluating the effect of SEMA3G in vivo, we performed CellChat analysis and identify the tumor cells as primary recipients of SEMA3G." (PMID 40533501, 2025). "Our findings indicated that the conditional deletion of Sema3G in ECs promoted tumor growth and accelerated mouse death." (PMID 40533501, 2025). "Then, the SEMA3G-overexpressed mice were orthotopically injected with GSC07-Luc cells to establish tumor models." (PMID 40533501, 2025). "In order to further probe the role of SEMA3G in tumor immune infiltration, we analyzed the expression correlation of SEMA3G with biomarkers of immune cells in KIRC determined by GEPIA database." (PMID 38070142, 2023). "Our current analytic result indicated that SEMA3G was positively correlated with tumor immune cell infiltration in KIRC, especially CD4+ T cell, macrophage, neutrophil and dendritic cell." (PMID 38070142, 2023). "Patient age, tumor grade, status of IDH mutation and expression of seven genes (SEMA3A, SEMA3D, SEMA3F, SEMA3G, ITGB3, ITGA5, and VEGFA) significantly correlated with patient OS (p < 0.05)." (PMID 33036421, 2020). "The overexpression of SEMA3G in U251MG cells inhibited tumor cell migration and invasion in vitro, and suppressed angiogenesis process, when SEMA3G overexpressing U87MG cells were implanted in the brain cortex of mice." (PMID 33036421, 2020). "Among the tumor specimens with IDH mutation, mRNA levels of SEMA3B, SEMA3C, SEMA3D, SEMA3G, NRP2, PLXNA2, and CDH1 were significantly higher (p < 0.05), while SEMA3F, NRP1, ITGB3, ITGA5, and VEGFA genes were under-expressed (p < 0.05)." (PMID 33036421, 2020). "In agreement with this study, we also noticed similar tendencies of SEMA3B, SEMA3G, SEMA3D and VEGFA mRNA level associations with patient survival and tumor malignancy grade." (PMID 33036421, 2020). "SEMA3G is another potential marker for adipogenesis, has an inhibitory effect on tumor progression, and takes part in controlling the function of endothelial cells and smooth muscle cells." (PMID 23922792, 2013). "Sema3A, sema3D, sema3E and sema3G overexpression in breast cancer cells significantly inhibits the development of tumor in xenograft models and decreases the number of intra-tumor blood vessels, suggesting an anti-angiogenic role of these molecules." (PMID 24212788, 2011). "We have presented here for the first time evidence indicating that sema3D, sema3G sema3E and sema3A can significantly reduce the concentration of microvessels in tumors that develop from tumor cells that express these semaphorins." (PMID 18818766, 2008).